CARMIL3 (capping protein regulator and myosin 1 linker 3)
Synonyms: C14orf121; LRRC16B; BC008134; crml-1
Tractability: Antibody: UniProt places it where antibodies can reach, with high confidence; its Gene Ontology location is reachable by antibodies, with high confidence.
Gene: Protein-coding gene on chromosome 14 (24,052,009 to 24,069,734, forward strand). Ensembl gene ENSG00000186648.
Subcellular location: Cytoplasm; Cell membrane
Gene Ontology:
Biological process: cell migration; regulation of Arp2/3 complex-mediated actin nucleation; regulation of postsynapse assembly
Cellular component: cytoplasm; plasma membrane; lamellipodium; glutamatergic synapse; postsynapse
Genetic constraint (gnomAD): Loss-of-function variants: 88 observed, 183.16 expected, observed/expected ratio (o/e) 0.48, 90% interval 0.4 to 0.57. The upper end of that interval is the gene's LOEUF score, 0.57, which puts it in group 2 of 6, group 1 being the genes least tolerant of losing a copy. Missense variants: 1,548 observed, 1,822.8 expected, observed/expected ratio (o/e) 0.85, 90% interval 0.81 to 0.89. Synonymous variants: 694 observed, 732.1 expected, observed/expected ratio (o/e) 0.95, 90% interval 0.89 to 1.01.
Homologues: Orthologues: chimpanzee CARMIL3 (99% identical), macaque CARMIL3 (98% identical), rabbit CARMIL3 (96% identical), pig CARMIL3 (96% identical), guinea pig CARMIL3 (96% identical), mouse Carmil3 (95% identical), rat Carmil3 (95% identical), dog CARMIL3 (93% identical), zebrafish carmil3 (46% identical), tropical clawed frog carmil3 (44% identical), Drosophila melanogaster LRR (28% identical), Caenorhabditis elegans crml-1 (20% identical). Paralogues in human: CARMIL1 (37% identical), CARMIL2 (32% identical), PPP1R37 (10% identical), RNH1 (8% identical).
Diseases named in the same sentence as CARMIL3 in open-access papers:
CARMIL3 is named in the same sentence as 5 diseases in open-access papers, as found by Europe PMC text mining. Sharing a sentence is not in itself a finding about the gene and the disease. The quoted sentences say what the papers report.
Cerebral ischemia (1 paper, 2021). Restriction of arterial blood supply to the brain associated with insufficient oxygenation to support the metabolic requirements of the tissue. "Third, there was a lack of experimental data on the functions of CARMIL3 in cerebral ischemia." (PMID 34975397, 2021).
ischemia (1 paper, 2021). A hypoperfusion of the BLOOD through an organ or tissue caused by a PATHOLOGIC CONSTRICTION or obstruction of its BLOOD VESSELS, or an absence of BLOOD CIRCULATION. "As CARMIL3 immunoreactivity was associated with larger neuronal cell bodies and neurites, we hypothesized that cell edema induced by ischemia underlay this phenomenon." (PMID 34975397, 2021). "The low expression of CARMIL3 in the T2(+) regions in 3 days after pMCAO showed that the increase of CARMIL3 within 4.5 h of ischemia was a transient phenomenon." (PMID 34975397, 2021).
ischemic stroke (1 paper, 2021). A stroke disorder caused by obstruction of blood flow to the brain, due to thrombotic (local blood clot formation) or embolic (due to a blood clot or other material traveling from another site) event. "We then conducted the following experiments to verify the expression and characterize the cell biology of CARMIL3 in ischemic stroke." (PMID 34975397, 2021).
Stroke (1 paper, 2021). Sudden impairment of blood flow to a part of the brain due to occlusion or rupture of an artery to the brain. "To investigate the pathological significance of CARMIL3, we analyzed its expression patterns in the rat stroke brain." (PMID 34975397, 2021). "To validate whether such a pattern of CARMIL3 expression is an ischemic signature of neurons in the human brain, we examined the resected infarcted human brain tissues and stroke-free autopsied brain tissues with CARMIL3 immunohistochemical staining." (PMID 34975397, 2021). "Given that CARMIL3 is increased in the infarct brain regions starting from the early hours, it may be detectable in the blood of stroke patients, which possibly has the potential as a biomarker of stroke severity." (PMID 34975397, 2021).
tumor (1 paper, 2021). "The known functions of CARMIL3 include enhancing tumor metastasis through promoting cell migration, adhesion, invasion, and metastatic colonization; promoting cell migration in immune cells; and regulating synapse maturation in developing perinatal brains." (PMID 34975397, 2021).